PODN (podocan)
Description:
Negatively regulates cell proliferation and cell migration.
Synonyms: SLRR5A; PCAN; MGC24995
Tractability: Antibody: UniProt places it where antibodies can reach, with medium confidence; UniProt predicts a signal peptide or a membrane-spanning region; its Gene Ontology location is reachable by antibodies, with medium confidence.
Gene: Protein-coding gene on chromosome 1 (53,061,293 to 53,093,681, forward strand). Ensembl gene ENSG00000174348.
Subcellular location: Secreted, extracellular space, extracellular matrix (Isoform 1); Cytoplasm (Isoform 2); Cytoplasm (Isoform 3); Cytoplasm (Isoform 4)
Gene Ontology:
Molecular function: collagen binding; extracellular matrix structural constituent conferring compression resistance
Biological process: negative regulation of cell migration; negative regulation of cell population proliferation
Cellular component: cytoplasm; extracellular matrix; extracellular region; gel phase of interstitial matrix
Genetic constraint (gnomAD): Loss-of-function variants: 38 observed, 49.17 expected, observed/expected ratio (o/e) 0.77, 90% interval 0.6 to 1.01. The upper end of that interval is the gene's LOEUF score, 1.01, which puts it in group 4 of 6, group 1 being the genes least tolerant of losing a copy. Missense variants: 691 observed, 801.87 expected, observed/expected ratio (o/e) 0.86, 90% interval 0.81 to 0.92. Synonymous variants: 389 observed, 370.12 expected, observed/expected ratio (o/e) 1.05, 90% interval 0.97 to 1.14.
Homologues: Orthologues: chimpanzee PODN (99% identical), macaque PODN (98% identical), rabbit PODN (93% identical), dog PODN (93% identical), guinea pig PODN (93% identical), pig PODN (93% identical), mouse Podn (91% identical), rat Scp2 (82% identical), tropical clawed frog podn (60% identical), zebrafish podn (54% identical). Paralogues in human: PODNL1 (46% identical), LRRC15 (22% identical), FLRT1 (19% identical), NYX (19% identical), FLRT3 (18% identical), FLRT2 (18% identical), LRRC4B (16% identical), LRRTM1 (16% identical), ASPN (16% identical), LRRC4C (16% identical), LRRTM4 (16% identical), LRRTM3 (15% identical), and 10 more.
Diseases named in the same sentence as PODN in open-access papers:
PODN is named in the same sentence as 12 diseases in open-access papers, as found by Europe PMC text mining. Sharing a sentence is not in itself a finding about the gene and the disease. The quoted sentences say what the papers report.
osteosarcoma (2 papers, 2021 to 2025). A usually aggressive malignant bone-forming mesenchymal neoplasm, predominantly affecting adolescents and young adults. "The area under the receiver operating characteristic curve (AUC value) was 0.855, which indicated that the expression of PODN had a good diagnostic value for osteosarcoma." (PMID 34273970, 2021). "The area under the ROC curve (AUC value) was 0.855, indicating that the expression of PODN has a good diagnostic value for osteosarcoma." (PMID 34273970, 2021). "It was identified that PODN was a prognostic biomarker and correlated with immune infiltrates in osteosarcoma, and was correlated with immune infiltrates in osteosarcoma." (PMID 34273970, 2021). "In this study, new molecules were found be aberrantly expressed in osteosarcoma, which suggested the potential value of PODN." (PMID 34273970, 2021). "Then, we found that PODN was significantly different between normal samples and osteosarcoma patients." (PMID 34273970, 2021). "Likewise, PODN gene expression decreases in osteosarcoma, with patients showing higher PODN expression having better survival rates than those with lower levels." (PMID 41463344, 2025). "Finally, it was determined that PODN has functional relevance in osteosarcoma and additional genes (ACTA2, COL6A1, FAP, OLFML2B and COL6A3) have prognostic significance for osteosarcoma." (PMID 34273970, 2021). "PODN was regarded as a potential biomarker for the diagnosis and prognosis of osteosarcoma, ACTA2, COL6A1, FAP, OLFML2B and COL6A3, can be used as potential prognostic indicators for osteosarcoma." (PMID 34273970, 2021).
pancreatic cancer (2 papers, 2021 to 2023). "These in silico results were validated using 43 pairs of resected pancreatic cancer samples, which also showed that the expression levels of MAGEH1, MAP3K3 and PODN were downregulated in tumor tissues." (PMID 33912458, 2021).
breast carcinoma (1 paper, 2025). "Specifically, the PG gene signature study identifies PODN among the downregulated genes in breast carcinomas and links its lower expression to advanced tumour stages and poor prognosis profiles." (PMID 41463344, 2025). "More recent evidence in breast carcinoma models confirms that PODN is significantly downregulated in tumour tissue compared with normal breast tissue and that this reduction is associated with a more malignant phenotype in BC." (PMID 41463344, 2025).
cardiac hypertrophy (1 paper, 2022). "This was supported by an abstract showing increased cardiac hypertrophy in Podocan deficient mice after induced pressure overload." (PMID 35669474, 2022).
fibrosis (1 paper, 2025). the formation of excess fibrous connective tissue in an organ or tissue in a reparative or reactive process. "CCDC80, LAMA4, PDGFRB, PODN, and SPARC are potential mediators of intestinal fibrosis due to common expression among ileal and colonic strictures." (PMID 40398622, 2025).
focal segmental glomerulosclerosis (1 paper, 2021). A renal disorder characterized by sclerotic lesions in the glomeruli. "And, they elucidate that the imbalance of podocan expression in (HIVAN) of HIV-a-associated nephropathy may lead to the pathogenesis of (FSGS) in focal segmental glomerulosclerosis." (PMID 34273970, 2021).
infarction (1 paper, 2025). A localised pathological necrosis of tissue resulting from obstruction of the blood supply usually by a thrombus, an embolus, or vascular torsion. "Furthermore, the increase in remodeling-related proteins, including EPHA4, PODN, and ALPK3, pointed to favorable structural adaptation following infarction." (PMID 41373456, 2025).
tumor (6 papers, 2020 to 2025). "In LSCCs, three significant expression alterations that were not detectable in RSCCs were observed specifically PRELP, CHAD and PODN, all of which underwent downregulation in the tumor tissues." (PMID 34440771, 2021). "The alteration in PODN expression was confirmed at the protein level through immunohistochemistry (p < 0.001, Wilcoxon test), which evidenced moderate to intense expression in absorptive cells and moderate staining in the stroma of healthy tissue, with only weak staining found in tumor cells." (PMID 34440771, 2021). "In our risk model, the expression of five genes (PODN, NPY, MICU3, TUBB6 and RHOJ) was decreased in tumor tissues, and the greater the degree of downregulation was, the better the prognosis was, indicating that the hypermethylation of these genes may play a protective role in GC patients." (PMID 32174791, 2020). "Finally, MAGEH1, PODN, and MAP3K3 were identified as three mRNAsi-related tumor suppressor genes that were downregulated in tumor tissues and whose overexpression was associated with prolonged OS." (PMID 33912458, 2021).
cancer (5 papers, 2010 to 2023). A tumor composed of atypical neoplastic, often pleomorphic cells that invade other tissues. "We then screened 12 hub genes from the blue module based on MM and GS, such as PODN, DCN, CCDC80, SVEP1 and AEBP1, which were reported to be predictive biomarkers and correlated with immune infiltration in various cancers." (PMID 36768989, 2023).
PODN also shares sentences with these, for which no sentence is quoted: gastric cancer (2 papers); prostate carcinoma (2); Nephropathy (1).